BCL11B (BCL11 transcription factor B)
Diseases named in the same sentence as BCL11B in open-access papers (continued):
Sharing a sentence is not in itself a finding about the gene and the disease.
tumor (continued). "The main functions of the top genes in OSPC2 network were associated to sensitization to chemotherapy (CXCR4, ANKRD1, CYR61, EDN1, ATP1B1, ARHGEF1, RTF1), and tumor suppression (FGFR3, BCL11B)." (PMID 28482906, 2017). "Consistently, we found that overexpression of KLF4, an indicated tumor suppressor gene in T-ALL, promoted the SUMOylation and degradation of BCL11B in T-ALL, suggesting that BCL11B acted as an oncogene in T-ALL." (PMID 25644173, 2015). "The ectopic expression of BCL11B in BCL11B-negative HeLa and hematopoietic progenitor FDC-P1cell lines suppress tumor growth by inducing cell cycle arrest." (PMID 23383087, 2013). "Upregulation of anti-apoptotic genes, including BAG1, BCL11B and SERPINB2, and downregulation of apoptotic genes, such as DAPK2, HRK and TP53INP1, can promote tumor cell survival." (PMID 23024765, 2012). "The PFS (2608 vs. 480 days, p < 0.0001) and OS (3570 vs. 1564 days, p < 0.01) were significantly longer in the BCL11B‐negative tumor cell group." (PMID 37293953, 2023). "The introduction of Bcl11b into cultured tumor cell lines lacking the expression of Bcl11b exhibited a suppressive effect of Bcl11b on tumor cell growth." (PMID 33804471, 2021). "Therefore, RNAseq was performed on tumor RNA, and reads were aligned with the HPV70 segment‐containing BCL11B gene." (PMID 31407403, 2020). "The viral DNA insertion allele comprised a minority fraction of all the BCL11B loci present in the tumor cell population, with the BCL11B copy number being highly nonuniform among the tumor cells." (PMID 31407403, 2020). "For CD99, 81% of non-EwS tumor samples were classified consistently across all three cores per sample, for BCL11B 97.6%, and for GLG1 and 94.8%, indicating only little intra-tumoral heterogeneity in EwS differential diagnoses." (PMID 32164354, 2020). "Therefore, the heterogeneity of scoring for CD99, BCL11B, and GLG1 in different cores per sample, originating from different regions of a given tumor block, was assessed." (PMID 32164354, 2020). "TP63 has previously been shown to be expressed in the tumour cells in human ACP, but APCDD1L and BCL11B have not been implicated in ACP." (PMID 29541918, 2018). "Nevertheless, it was puzzling that no tumour development has ever been reported in mice transplanted with Bcl11b homozygous knockout progenitors from fetal live." (PMID 25408871, 2012). "In conclusion, we believe that the data presented here strengthen the role of BCL11B in tumor survival rather than development." (PMID 20824091, 2010). "Furthermore, BCL11B could suppress CSC traits, as evidenced by dramatically decreased tumor spheroid formation, self-renewal potential and drug resistance." (PMID 33093445, 2020). "In addition, BCL11B could inhibited LGR5 expression and downregulated the activity of the β-catenin pathway, thereby attenuating cell regeneration and impairing tumor development in colorectal cancer." (PMID 33093445, 2020). "This suggests that BCL11b is not just a mere marker of genetically more differentiated blasts, but may act as a maturation dependent tumor suppressor, which is supported in other studies." (PMID 25023966, 2014). "We speculate that in non-transformed tissue BCL11B could control the proliferation, ensure genome stability and prevent tumor development and/or apoptosis." (PMID 20824091, 2010). "For non-EwS cases, the proposed marker combination of CD99, BCL11B, and GLG1 yielded a consistent classification over all 3 cores taken from different areas of each tumor sample in 95.2%." (PMID 32164354, 2020).
cancer (36 papers, 2009 to 2025). A tumor composed of atypical neoplastic, often pleomorphic cells that invade other tissues. "They found that increased Bcl11b expression was associated with poorly differentiated tumors and was colocalized with the cancer stem cell marker BMI1." (PMID 33363142, 2020). "Regarding the relationship between BCL11B and HCC, only a few studies have reported BCL11B gene modification by mutation, deletion, amplification, truncation, gain, and copy number aberrations, immune evasion mechanisms, and retention of cancer stem cell traits in HBV‐related HCC." (PMID 37293953, 2023). "The potential roles and interactions of Bcl11b and Tspan8 with Mycn in cancers characterized by Mycn overexpression warrant further investigation." (PMID 40862719, 2025). "Intriguingly, the mice that received the Bcl11b-KO cells acquired tumors much earlier and faster than the control recipient mice, ultimately exhibiting a much higher cancer incidence with age." (PMID 38886378, 2024). "Recently, it has been described a dual role of BCL11B in oncogenesis in such a way that, when overexpressed, it promotes the survival of cancer cells by avoiding cancer cell damage and cooperating with RAS oncogene in transformation." (PMID 38472338, 2024). "LEF1, WT1 and BCL11B copy number abnormalities were reported from the TARGET study of 2471 pediatric cancer patients whereas in our group we found CDKN2A, CDKN2B and MTAP harboring most copy number variations." (PMID 38459434, 2024). "At the single cell transcription level, Bcl11b expression was higher in gut mucosal cancer samples from patients compared with normal tissues, especially in stem cell/TA cell clusters." (PMID 39433900, 2024). "On the other hand, several studies have reported the effect BCL11B on cell proliferation and chemoresistance in cancer as an oncogene." (PMID 37293953, 2023). "B cell chronic lymphocytic leukemia/lymphoma 11B (BCL11B) is a Kruppel-like C2H2 type zinc finger transcriptional factor relating to various malignant tumors." (PMID 36918563, 2023). "Allelic deletion series that we engineered in a large “gene desert” downstream Bcl11b in mice displayed striking developmental and cancer phenotypes." (PMID 36950387, 2023). "The data further indicate that Mycn’s interactions with Bcl11b and Tspan8 may differ between cancer and normal tissues, exhibiting a more direct interaction, observed in cancer tissues." (PMID 40862719, 2025). "This suggests that combining BCL11B inhibition with chemotherapy could increase the efficacy of targeting cancer cells." (PMID 35563322, 2022). "The major finding of the study demonstrated that Bcl11b is overexpressed in all stages of MF as compared to benign inflammatory dermatosis and its expression was downregulated upon interferon treatment leading to increased cancer cell apoptosis." (PMID 33363142, 2020). "The distinct and contrasting functions of BCL11B in different cancers might be attributed to the complexity and heterogeneity of CSCs." (PMID 33093445, 2020). "The combined use of Bcl11b and Thy1 confirmed the existence of cellular intermediates sharing transcriptomic but also epigenomic traits, therefore providing a concrete demonstration of the previously proposed correlative analogies between cancer and reprogramming." (PMID 36075976, 2022). "The transcription factor B Cell Lymphoma/Leukemia 11B (BCL11B) exerts a bi‐directional function in cancer, with its role as an emerging therapeutic target in cancer treatment being particularly intriguing." (PMID 39976228, 2025). "BCL11B positively and significantly correlated with TRPA1 in CHOL, GBM, KICH and PRAD cancers." (PMID 39770499, 2024).
hematological malignancies (11 papers, 2006 to 2024). "A clinically relevant protein, especially in the context of hematologic diseases, is B-cell lymphoma/leukemia 11B (BCL11B)." (PMID 34946663, 2021). "The role of BCL11B, which is a main maturation factor of T cells, in hematologic malignancies is still discussed." (PMID 29352181, 2018). "BCL11B alterations are related to malignant T-cell transformation that occurs in hematological malignancies, regulating the apoptotic process and cell proliferation." (PMID 29207605, 2017). "BCL11B gene alterations are related to malignant T-cell transformation in hematological malignancies." (PMID 26186352, 2015). "BCL11B gene alterations are related to malignant T cell transformation that occurs in hematological malignancies." (PMID 23211040, 2012). "This review summarizes current data and knowledge concerning the alteration of BCL11B in hematological malignancies and its role as a potential target for therapies directed against T cell malignancies." (PMID 23211040, 2012). "Aberrations of BCL11B locus leading to abnormal gene transcription were identified in human hematological disorders and corresponding animal models." (PMID 20824091, 2010). "All five genes are essential to myeloid (EHZF), megakaryocytic (FOG1 and FOG2), T-lymphoid (BCL11B) and B-lymphoid (BCL11A) development; three (BCL11A and B, EHZF) have been implicated in hematological malignancy." (PMID 16704730, 2006). "The role of BCL11B in the pathogenesis of hematological diseases is controversial." (PMID 23383087, 2013). "The role of BCL11B in the pathogenesis of hematological diseases is still a matter of debate." (PMID 20824091, 2010). "Monoallelic defects in the BCL11B gene leading to loss-of-function are associated with a wide spectrum of phenotypes, including neurological disorders with or without immunological features and susceptibility to hematological malignancies." (PMID 38472338, 2024).
neurodevelopmental disorder (10 papers, 2019 to 2025). A behavioral and cognitive disorder with onset during the developmental period that involves impaired or aberrant development of intellectual, motor, or social functions. "The BCL11B‐related neurodevelopmental disorders are rare, and only 17 variants in 25 patients have been found to date." (PMID 36683525, 2023). "This study identified a new splice variant and a novel frameshift variant of the BCL11B gene in two unrelated pedigrees, including 3 patients in Family 1 and 1 patient in Family 2 with neurodevelopmental disorders." (PMID 36176959, 2022). "This is the first report of non-syndromic neurodevelopmental disorder caused by a BCL11B variant in a Chinese population." (PMID 33072985, 2019). "The BCL11B‐related neurodevelopmental disorder was rare, only 14 variants were found to date." (PMID 36683525, 2023). "The findings of this study expand the mutation spectrum of the genetic BCL11B gene, which not only improves the understanding of the associated neurodevelopmental disorders from a clinical perspective but also provides guidance on diagnosis and genetic counseling for patients." (PMID 36176959, 2022). "It links fundamental experimental research with the emerging amount of clinical and genetic data from individuals affected by Bcl11a- and Bcl11b-dependent neurodevelopmental disorders." (PMID 38392344, 2024). "Computational analyses of gene/mRNA regulatory interactions implicate known neurodevelopmental disorder risk genes (CHD8, TCF4, FMRP, BCL11B and TBR1) as regulators of this cascade and reveal pathways through which they may contribute to disease." (PMID 35031607, 2022).
infection (6 papers, 2016 to 2025). The state of being infected such as from the introduction of a foreign agent such as serum, vaccine, antigenic substance or organism. "TRBV6-5 and BCL11B are primarily implicated in the immune response post-infection; PTGDS, EGR3, and CXCR5 modulate the host’s inflammatory response." (PMID 39591343, 2024). "We individually altered the expression levels of IRF1, GATA1, and Bcl11b 24 h post-infection with ALV-J." (PMID 40075948, 2025). "Most significantly, however, 15- to 20-fold fewer B8R20–27/kb-reactive memory CD8+ T cells were present in the spleen and lungs 42 days after infection of Bcl11b−/− mice vs. WT mice." (PMID 27790219, 2016). "Thus, Bcl11b confers competitive fitness to memory cells located in the lung regardless of whether infection is via the peritoneal cavity or respiratory tract." (PMID 27790219, 2016).
neurological disorders (5 papers, 2011 to 2024). "Regarding the pattern of inheritance, it is striking that 100% of the disease-causing variants in BCL11B-neurological disorders were of germline origin, either de novo or inherited from an affected parent." (PMID 38472338, 2024). "Rare missense variants causing BCL11B haploinsufficiency are also responsible for some cases of neurological disorders." (PMID 38472338, 2024). "Most BCL11B target genes in these pathways have been previously implicated in at least one of these three neurologic disorders." (PMID 37519464, 2023). "Moreover, there are reports suggesting that BCL11B serves as a novel regulatory factor in the brain-derived neurotrophic factor (BDNF) signaling pathway 30, which is disrupted in many neurological disorders." (PMID 39239553, 2024).
bacterial infection (2 papers, 2013 to 2024). "Bcl11b is associated with the Cd8 enhancers E8I, E8IV, and E8V and Bcl11b is necessary to maintain CD8 expression in mature CD8+ T cells during bacterial infection as well as during in vitro activation." (PMID 23793512, 2013).
brain disorder (2 papers, 2024). A disease affecting the brain or part of the brain. "Moreover, the existence of such cell-type-specific signaling modules reveals how a fundamental transcription factor with diverse functions such as Bcl11b can be implicated in the pathogenesis of brain disorders characterized by synaptic dysfunction." (PMID 38358390, 2024).
inherited diseases (1 paper, 2022). "During the last two decades, extensive knowledge has been accumulated about the physiological role of BCL11B and the role of its mutations in inherited diseases." (PMID 35563322, 2022).
psychiatric disease (1 paper, 2023). "Together, these findings lead to the hypothesis that BCL11B regulates important signaling processes in MSNs and cortical neurons, whether shared or distinct, that may be particularly vulnerable to psychiatric disorder risk variants and HD pathogenesis." (PMID 37519464, 2023). "Our study reveals significant enrichment of psychiatric disorder risk genes in BCL11B-regulated signaling, including cAMP-dependent protein kinase A (PKA) and DARPP32 signaling, specifically in MSNs, and calcium and glutamatergic synaptic signaling in both neuronal types." (PMID 37519464, 2023). "Furthermore, our study predicts involvement of BCL11B target genes in regulating these pathways, with many genes identified either as risk factors for or differentially expressed in psychiatric disorders." (PMID 37519464, 2023). "This suggests that BCL11B-associated phenotypes may contribute to neuropathology in SCZ and that there might be yet undiscovered MSN dysfunction in this psychiatric disease development." (PMID 37519464, 2023). "Indeed, we demonstrate that BCL11B-dependent cAMP-PKA-calcium signaling and DA-DARPP32 signaling pathways in MSNs are enriched for psychiatric disorder risk variants, pointing to a potential role for BCL11B-associated phenotypes in neuropathology in these disorders." (PMID 37519464, 2023). "In conclusion, we identify BCL11B-regulated molecular mechanisms in striatal and cortical neurons and further strengthen the hypothesis that MSN dysfunction may contribute separately from cortical neuron pathology to psychiatric disease development." (PMID 37519464, 2023).
BCL11B also shares sentences with these, for which no sentence is quoted: HIV-1 infection (5 papers); autism (3); helminth infection (3); adult T cell leukemia (2); amyotrophic lateral sclerosis (2); neurodegenerative disease (2); rhabdomyosarcoma (2); allergic contact dermatitis (1); alopecia (1); Apert syndrome (1); bacteremia (1); blood cancer (1); Brain atrophy (1); cardiovascular disease (1); chronic myelogenous leukemia (1); combined immunodeficiency (1); craniofrontonasal syndrome (1); dermatitis (1); diabetes (1); Down syndrome (1); dysplasia (1); embryonic carcinoma (1); encephalitis (1); eosinophilic esophagitis (1); head and neck tumors (1); hearing loss (1); heart failure (1); hematopoietic cancers (1); Hodgkins lymphoma (1); hypertrophic cardiomyopathy (1).
A further 22 diseases each share a sentence with BCL11B in 1 paper.